NTRK2 (neurotrophic receptor tyrosine kinase 2)
Diseases named in the same sentence as NTRK2 in open-access papers (continued):
Sharing a sentence is not in itself a finding about the gene and the disease.
neuroblastoma (continued). "Whether NGFR upregulation is instrumental and causal for the enhanced expression of NTRK2, NEFL, TUBB3, and MAP2 that we observe in the L-AN-5 neuroblastoma system, remains to be investigated." (PMID 33174841, 2020). "Another study confirmed that miR-204 binds to BCL2 mRNA in a neuroblastoma cell line and showed that it may also bind to NTRK2 (neurotrophic receptor tyrosine kinase 2)." (PMID 29382303, 2018). "However, NTRK2 expression has been found to be induced by HIF-1 transcriptional activator in neuroblastoma cells." (PMID 27672444, 2016). "The differential localization of NTRK1/TrkA, which preferred endosomes, and NTRK2/TrkB, which was enriched in DRMs may provide a clue as to how these two similar receptors have such profoundly different effects in neuroblastoma." (PMID 25884760, 2015). "Moreover, PHLDA1 downregulation was shown to affect differentiation-associated transcripts such as ID1, ID2 (encoding inhibitors of differentiation 1, 2), NTRK1, NTRK2 (encoding tropomyosin receptor A, B), and NGF (encoding nerve growth factor) in IMR-32 neuroblastoma cells." (PMID 39630301, 2025). "In this regard, low-risk neuroblastoma is common in younger children with <18 months of age at the time of diagnosis and NTRK1 expression (encoding TRKA) is a strong prognostic histological marker for favorable cases, whereas TRKB (encoded by NTRK2) is associated with poor outcome." (PMID 34493726, 2021). "Similarly to the effect of ATRA treatment, the overexpression of NTRK2 triggered the cell differentiation, and this supports our hypothesis that ATRA influences neuroblastoma differentiation by regulating the expression of NTRK2." (PMID 32149119, 2020). "Our study systematically provided the potential regulatory information of ATRA-triggered neuroblastoma differentiation, and in the NTRK2 gene, we identified a novel RA response DNA element, which may contribute to the differentiation in a human-specific manner." (PMID 32149119, 2020). "Western blot analysis of cytosolic and membrane fractions isolated from Ba/F3 cells and the neuroblastoma cell line, SH-SY5Y, showed that NTRK2 ITD expression was restricted to the membrane fraction." (PMID 40348911, 2025). "Since induction of neural differentiation markers BCL2 and NTRK2 was suppressed, we compared the expression of VIM, a characteristic marker of S-type neuroblastoma cells, in untreated wild-type and TOP2B null SH-SY5Y cells." (PMID 35831557, 2022). "We surveyed our seven neuroblastoma cell lines for NTRK1,2,3 expression and demonstrated enhanced mRNA levels for NTRK2 and NTRK3 in all tested cell lines, as well as enhanced NTRK1 expression in 5 of 7 experimental cell lines." (PMID 29207623, 2017). "Similar to other genes identified in our analysis, the neurotrophin receptor TrkB (NTRK2) and the Wnt, β-estradiol and MAPK signalling pathways have all been shown to have a strong correlation with poor prognosis in neuroblastoma." (PMID 28187790, 2017). "NTRK1/TrkA is a marker for neuroblastoma tumors that spontaneously undergo apoptosis and regression, while NTRK2/TrkB is often expressed with its ligand, (BDNF), forming an autocrine loop that predicts poor prognosis." (PMID 25884760, 2015). "The SY5Y neuroblastoma cell line was stably transfected with NTRK1, NTRK2 or a vector control to generate these models, designated SY5Y-NTRK1, SY5Y-NTRK2 and SY5Y-vec, respectively." (PMID 25361003, 2014). "In contrast, high intratumoral expression of NTRK2 and its specific ligand, brain-derived neurotrophic factor (BDNF), enhances proliferation, metastatic behavior and chemoresistance in neuroblastoma cells." (PMID 25361003, 2014). "Neuroblastoma tumorigenesis is closely related to the expression of the neurotrophins and their specific receptors, the Trk family; TrkA, TrkB and TrkC (also known as NTRK1, NTRK2, and NTRK3, respectively)." (PMID 36831211, 2023).
neuroblastoma (continued). "Besides, a previous study reported that Neurotrophin Receptor TrkB (NTRK2) and Wnt β-Estradiol and MAPK signaling pathways are closely related to the worse prognosis of neuroblastoma." (PMID 35489022, 2022). "Functional genomic analysis and western blotting assay suggested that, in neuroblastoma cells, ATRA may directly regulate the NTRK2 gene by activating the RA receptor (RAR) that binds in its promoter region." (PMID 32149119, 2020). "NTRK1 and NTRK2 expression are indicative of excellent and poor clinical outcome in neuroblastoma, respectively, yet there is no data on the role of NTRKs in cell-cell communication mediated by extracellular vesicles." (PMID 32296437, 2020). "The results suggested that the NTRK2 gene may directly respond to ATRA treatment and the overexpression of NTRK2 can trigger neuroblastoma differentiation." (PMID 32149119, 2020). "Of note, cytotoxic activity of CD171-specific CAR T cells was independent of NTRK2 expression, which is a marker of aggressive neuroblastoma." (PMID 32296437, 2020). "Since neurotrophin receptor expression on neuroblastoma cells is known to have an effect on immune cells, we investigated whether NTRK1 or NTRK2 expression influences CAR T cell efficacy." (PMID 32296437, 2020). "Several RTKs, including ALK, KIT, MET, NTRK2, and RET, play a major role in neuroblastoma pathogenesis, and their activation could be responsible for adaptive resistance to trametinib and ganitumab in neuroblastoma." (PMID 39001383, 2024). "It remains to be elucidated whether NTRK2 inhibition by small molecules, which is highly effective against preclinical neuroblastoma models, would further improve CAR T cell therapy against NTRK2-expressing neuroblastomas." (PMID 32296437, 2020). "Since TEVs, regardless of their derivation from NTRK1- or NTRK2-expressing cells, display obstructing effects on CD4+ CAR T cells in vitro, it should be tested whether CD8+ CAR T cells are a better suited for cell-based neuroblastoma immunotherapy." (PMID 32296437, 2020).
Cognitive impairment (113 papers, 2012 to 2025). Abnormal cognition is characterized by deficits in thinking, reasoning, or remembering. "In contrast, marked cognitive deficits have been described in reports on patients with BDNF heterozygosity or mutations in the gene encoding for TrkB and NTRK2." (PMID 37491857, 2024).
Obesity (106 papers, 2007 to 2025). Accumulation of substantial excess body fat. "Considering that mutations in Bdnf and Ntrk2 are also associated with hyperphagia and obesity in humans, these advances in knowledge are significant and necessary." (PMID 38672441, 2024). "NTRK2 heterozygous mutations have been described in human syndromes of obesity and developmental delay." (PMID 38019584, 2024). "Patients with a heterozygous missense mutation, Y722C in Ntrk2, have severe hyperphagia and obesity, diminished learning and memory, and impaired detection of painful stimuli." (PMID 38672441, 2024). "Patients carrying monogenic mutations in either BDNF or NTRK2 (encoding TRKB) experience severe hyperphagic obesity." (PMID 37956053, 2023). "Neurotrophic receptor tyrosine kinase-2 (NTRK-2) encodes for the neurotrophin receptor TrkB, that that has also previously been linked to the regulation of energy homeostasis with mutations in NTRK2 being associated with severe early onset obesity in children." (PMID 37456561, 2023). "The two cell types also expressed Bdnf (ESμ=0.91, ESμ=0.99); mutations in BDNF and its receptor, NTRK2, is a known cause of monogenic obesity in humans and, in mice, BDNF signaling is required for normal energy homeostasis and glucoregulatory control." (PMID 32955435, 2020). "The TrkB receptor is critical for the control of energy balance, as mutations in its gene (NTRK2) lead to hyperphagia and severe obesity." (PMID 32265438, 2020). "Mutations in the gene encoding TrkB, NTRK2, have been associated with monogenetic severe obesity with developmental delay." (PMID 32982666, 2020). "The neurotrophic tyrosine kinase receptor type 2 (NTRK2) gene was screened in a boy with early onset obesity, hyperphagia developmental delay, impairments in short-term memory and impaired nociception, revealing a missense mutation in NTRK2." (PMID 25825681, 2015). "Homozygous mutations in the gene encoding TrkB (Ntrk2) are lethal in mice, but heterozygous mutations resulting in 25% of TrkB expression display hyperphagia, increased linear growth and obesity as well as complex neurobehavioral phenotypes." (PMID 25825681, 2015). "Clinically, disruption of POMC, PCSK1, BDNF, and NTRK2 is associated with severe early-onset obesity." (PMID 25806089, 2015). "Although none of the known positional genes have been reported to have a direct functional relevance to kidney function, NTRK2 was selected to screen for SNPs in the present study based on its association with obesity." (PMID 25885044, 2015). "Additionally, we found a novel heterozygous variant in the BDNF receptor gene, NTRK2 gene c.1726C>T p.L576F, in a 4-year-old Qatari boy with obesity, hyperphagia, acanthosis nigricans, and obstructive sleep apnea." (PMID 37329217, 2023). "Mutations of NTRK2 have been associated with obesity and eating behavior." (PMID 36997916, 2023). "Inherited obesity and polygenic obesity (stemming from multiple and synergistic polymorphisms) are thought to involve brain, signaling, and nervous system genes such as NTRK2, KCNQ1, MRAP2, and ADCY3 that regulate satiety and thermo-caloric energy balance." (PMID 36143948, 2022). "Interestingly, a latest study reports an atypical Charcot–Marie–Tooth disease type 2Q phenotype with obesity likely related to the mutation identified in the coding region of the NTRK2 gene." (PMID 34833132, 2021). "Mutations in the NTRK2 gene, which codes for TrkB, lead to severe obesity in mice and humans." (PMID 32265438, 2020). "Interestingly, even unilateral Ntrk2 gene deletion was sufficient to cause significant obesity, indicating that normal energy homeostasis needs full-strength TrkB signaling in PVH neurons that control appetite." (PMID 32265438, 2020). "De novo NTRK2 mutations, a highly intolerant gene to both loss-of-function (pLI = 1) and missense variants (miss-z = 4.35), have been previously associated with severe obesity and developmental delay." (PMID 30926952, 2020).
Obesity (continued). "Mutations in NTRK2 have been associated with obesity and eating disorder in man." (PMID 25885044, 2015). "Similar to the phenotype of Bdnf+/− heterozygotes, Ntrk2 hypomorphic mice also show hyperphagia, increased fat accumulation and obesity." (PMID 38019584, 2024). "Twenty-one of these eGenes were detected only in GM and include genes with a role in diseases such as cancer (e.g. LUZP6 PCDHB13) and obesity (e.g. NTRK2), narrowing down the list of genes that constitute promising candidates for further study." (PMID 37543566, 2023). "We also highlight context-specific regulatory effects for genes involved in metabolic (e.g. obesity, NTRK2,) and neurological (e.g. schizophrenia, MAN2A1,) diseases, and for genes with a role in biological processes such as adipogenesis (e.g. DEPTOR,)." (PMID 37543566, 2023). "In a study of 25 obese Guadeloupean patients, 5 heterozygous variants in 4 monogenic obesity genes (MC4R, NTRK2, SH2B1, and SIM1) were detected with a prevalence of 10%." (PMID 37329217, 2023). "Other mutations within the leptin–melanocortin pathway, such as in proopiomelanocortin (POMC), melanocortin receptor 4 (MC4R), brain-derived neurotrophic factor (BDNF), and the tyrosine kinase receptor B (NTRK2) genes, can also contribute to obesity." (PMID 37762850, 2023). "We also identified CpGs and genes with links to obesity (NTRK2, PSTPIP2, MBIP) and glucose and fat metabolism (IRS1)." (PMID 37649101, 2023). "As to Ntrk2, a recent study revealed that Ntrk2 deletion in the dorsomedial hypothalamus (DMH) of mice caused obesity and hyperphagia." (PMID 33826123, 2022). "Because Ntrk2 deletion in the PVH produced more severe obesity in females than males, we used female mice to more sensitively uncover the role of different PVHTrkB projections in the control of appetite." (PMID 32265438, 2020). "Deletion of the Ntrk2 gene in either of these two subtypes of neurons led to hyperphagia and obesity." (PMID 32265438, 2020). "Here, we demonstrate that selective Ntrk2 deletion within paraventricular hypothalamus (PVH) leads to severe hyperphagic obesity." (PMID 32265438, 2020). "The observation that Ntrk2 deletion in the PVH leads to hyperphagic obesity would implicate PVHTrkB neurons in the acute regulation of food intake." (PMID 32265438, 2020). "Here, we found that some DMR genes are obesity genes or related to the former which have been studied by genomic and genome-wide association study (GWAS) methods, for example, FTO, PCSK5, PCSK6, NTRK2, ABCC4, TXNIP and RPS6KA2." (PMID 31637123, 2019). "To investigate the role of the adipose tissue BDNF/TrkB axis in obesity, we examined Bdnf and Ntrk2 expression in mice with dietary obesity owing to feeding with a high-fat/high-sucrose (HFHS) diet." (PMID 28721258, 2015). "We found significant changes of Bdnf and Ntrk2 expression in the adipose tissue of mice with dietary obesity, with Bdnf being upregulated and Ntrk2 being downregulated." (PMID 28721258, 2015). "Obesity caused by other genetic mutations in the leptin-melanocortin pathway include proopiomelanocortin (POMC) and melanocortin receptor 4 (MC4R), brain-derived neurotrophic factor (BDNF), and the tyrosine kinase receptor B (NTRK2) genes." (PMID 33511092, 2020). "Furthermore, we find that deletion of the Ntrk2 gene in the PVH leads to severe hyperphagic obesity." (PMID 32265438, 2020). "Interestingly, functional characterization of human NTRK2 mutations were identified in subjects with severe early-onset obesity and NTRK2 was involved in appetitive behavior." (PMID 28628658, 2017). "Mouse Bdnf mutants that express decreased amounts of Ntrk2 show hyperphagia and maturity-onset obesity, while risk variants in human BDNF were significantly associated with more food servings in a study of obesity susceptibility loci and dietary intake." (PMID 25760438, 2015).
Obesity (continued). "However, we found that Fabp4-Cre-induced deletion of Bdnf or Ntrk2 led to hyperphagia, obesity, and aggressiveness, presumably due to ectopic Fabp4-Cre mediated gene recombination in the brain." (PMID 28721258, 2015). "Important genes associated with monogenic obesity consist of leptin (LEP), leptin receptor (LEPR), proopiomelanocortin (POMC), prohormone convertase 1 (PCSK1), MC4R, single-minded homolog 1 (SIM1), brain-derived neurotrophic factor (BDNF), and its receptor NTRK2 (commonly referred to as TrkB)." (PMID 40428329, 2025). "The most frequent causes of monogenic obesity are mutations in the genes leptin (LEP), leptin receptor (LEPR), melanocortin 4 receptor (MC4R), proopiomelanocortin (POMC), proprotein convertase subtilisin/kexin type 1 (PCSK1), and neurotrophic receptor tyrosine kinase 2 (NTRK2)." (PMID 37375898, 2023). "Furthermore, Ntrk2 gene deletion in the PVH also led to obesity in male mice." (PMID 32265438, 2020). "In addition, Ntrk2 heterozygous mice do not show major abnormalities while loss of one NTRK2 (TrkB) allele in human leads to hyperphagic obesity and severe impairment in memory, learning and nociception." (PMID 31429825, 2019). "In addition, NTRK2 knockout mice developed obesity and hyperphagia." (PMID 28628658, 2017). "Notably, ChrSd supplementation lowered the hepatic expression of genes previously reported to be candidate genes for obesity, such as Insig-1, lepR, neurotrophic tyrosine kinase receptor type 2 (Ntrk2), melanocortin 5 receptor (Mc5r), and matrix metallopeptidase 7 (Mmp7)." (PMID 27977712, 2016). "Interestingly, Ntrk2 or Bndf homozygous knockouts are not viable, but Bndf heterozygous knockouts, as well as conditional deletion of Bndf in the postnatal brain and hypomorphic mice expressing 24% of normal levels of TrkB all exhibit increased food intake and obesity." (PMID 19742318, 2009). "Deleting Ntrk2 in PVNTrkB neurons that project to the VMH (PVNTrkB→VMH neurons) or to the LPBN (PVHTrkB→LPBN neurons) induces hyperphagia and obesity, highlighting that these TrkB neuronal projections are critical for suppressing appetite." (PMID 38672441, 2024). "The current study found a significant inverse correlation between birth weight and obesity and diabetes genes, including MTNR1B, NTRK2, PCSK1, and PTEN (r= -0.221, -0.235, -0.246, and − 0.418, respectively)." (PMID 36997916, 2023). "A significant inverse correlation between birth weight and obesity and diabetes genes, including MTNR1B, NTRK2, PCSK1, and PTEN genes (r= -0.221, -0.235, -0.246, and − 0.418, respectively)." (PMID 36997916, 2023). "We find that PVHTrkB neurons projecting to LPBN are distinct from those to VMH, yet Ntrk2 deletion in PVH neurons projecting to either VMH or LPBN results in hyperphagia and obesity." (PMID 32265438, 2020). "The observation that abolishment of Ntrk2 expression in PVHTrkB→VMH and PVHTrkB→LPBN neurons leads to hyperphagic obesity suggests that these two subtypes of neurons respond to changes in nutritional state." (PMID 32265438, 2020). "For example, Ntrk2 shows a similar induction pattern as CD36 and has also been shown to play a role in breast cancer cell survival and obesity." (PMID 25984797, 2015). "Our previous cancer and obesity studies identified BDNF as the key brain mediator for improved metabolic and immunity outcomes following EE, and our EE-BTBR study found that Bdnf and Ntrk2 were upregulated following EE." (PMID 36893171, 2023). "Sim1-Cre is expressed in other brain regions in addition to the PVH40, so the obesity phenotype in Sim1-Cre;Ntrk2lox/lox mice might result from Ntrk2 deletion in non-PVH neurons or cells." (PMID 32265438, 2020). "In addition, ROHs at 9q21.33-q22.2 and 17q22-q23.2 were found and contained genes (NTRK2, MKS1) that may play a role in obesity and developmental or speech delay." (PMID 25400949, 2014).
Obesity (continued). "Apart from the well-known obesity genes (LEP, PCSK1, NTRK2), we identified several BMI effector genes that have not been reported in GWAS but are supported by multiple converging lines of evidence." (PMID 38167462, 2024). "Deletion of the TrkB-coding Ntrk2 gene in the adult PVH results in hyperphagia and severe obesity without affecting energy balance." (PMID 35338053, 2022). "It is unlikely that this negative outcome is due to inadequate Ntrk2 deletion in NTS-projecting PVH neurons, as we showed that even unilateral Ntrk2 deletion in the PVH led to obesity." (PMID 32265438, 2020). "Although studies suggest that MC4R signaling interacts with BDNF-TrkB signaling in the context of body weight regulation, it is unlikely that Ntrk2 deletion in the PVH leads to obesity through the MC4R because the deletion did not reduce levels of Mc4r mRNA." (PMID 32265438, 2020).
Anxiety (100 papers, 2007 to 2026). Intense feelings of nervousness, tension, or panic often arise in response to interpersonal stresses. "Our current EPM data are in line with reduced anxiety in Ntrk2-deficient heterozygote mice and with a critical role of TrkB activation in enhanced anxiety-like behavior in mice after status epilepticus." (PMID 25309367, 2014). "BPA dysregulates Rsg4 transcription in cortical pyramidal neurons, leading to BPA-mediated abnormal synaptic formation, anxiety and mild cognitive dysfunction via regulation of BDNF/NTRK2 signaling." (PMID 35781563, 2022).